GPNMB (glycoprotein nmb)
Diseases named in the same sentence as GPNMB in open-access papers (continued):
Sharing a sentence is not in itself a finding about the gene and the disease.
amyotrophic lateral sclerosis (25 papers, 2015 to 2025). Amyotrophic lateral sclerosis (ALS) is a neurodegenerative disease characterized by progressive muscular paralysis reflecting degeneration of motor neurons in the primary motor cortex, corticospinal tracts, brainstem and spinal cord. "For instance, GPNMB is recognized as a neuroprotective factor that mitigates motor neuron degeneration in amyotrophic lateral sclerosis (ALS)." (PMID 40653468, 2025). "An increase in GPNMB levels in the brain has been found in a variety of neurodegenerative disorders, including AD, amyotrophic lateral sclerosis (ALS), and Parkinson’s disease (PD)." (PMID 37510803, 2023). "In a cellular amyotrophic lateral sclerosis model, it has been shown that GPNMB exerts neuroprotective effects by binding to Na/K-ATPase, an ion pump and receptor that modulates neuroinflammation." (PMID 36263422, 2022). "GPNMB has also been demonstrated to be neuroprotective in an animal model of amyotrophic lateral sclerosis, cerebral ischemia, and other disease models." (PMID 34103390, 2021). "Elevated CSF GPNMB levels have been suggested as a promising biomarker candidate in other neurological disorders such as amyotrophic lateral sclerosis (ALS) and neurological forms of Gaucher disease." (PMID 33947460, 2021). "More recently, the spinal cord of amyotrophic lateral sclerosis (ALS) patients was shown to exhibit increased expression of GPNMB compared to control patients, as well as increased GPNMB expression in animal models of both ALS and ischemic injury." (PMID 29519253, 2018). "GPNMB was upregulated in astrocytes and neurons in an animal model of amyotrophic lateral sclerosis, and secretion of the extracellular fragment by astrocytes had a neuroprotective effect." (PMID 29312322, 2017). "Besides, some evidence suggests that GPNMB expression is upregulated in the spinal cord of amyotrophic lateral sclerosis (ALS) patients." (PMID 37786733, 2022). "Furthermore, GPNMB has been shown to be elevated in brain and/or plasma of numerous neurodegenerative diseases such as Gaucher disease, Niemann-Pick Type C disease and amyotrophic lateral sclerosis (ALS)." (PMID 30340518, 2018). "So far, GPNMB has been reported to be involved in cancer diseases, non-alcoholic steatohepatitis, inflammatory bowel disease (IBD), Niemann Pick disease-type C, Gaucher disease, amyotrophic lateral sclerosis (ALS) and PD." (PMID 32983228, 2020). "Moreover, Tanaka and coll., provided evidence that GPNMB could have a potential protective role in neurodegenerative disorders, in particular in Amyotrophic Lateral Sclerosis (ALS), suggesting that the locus should be further investigated also in PD models and human post-mortem tissue." (PMID 27611585, 2016). "In the mouse model of amyotrophic lateral sclerosis (ALS) carrying the mutant superoxide dismutase (SOD1G93A) and ALS patients, GPNMB was greatly induced during the disease progression and it was especially expressed in the motor neurons and astrocytes." (PMID 26581806, 2015). "Glycoprotein nonmetastatic melanoma protein B (GPNMB) plays important roles in various types of cancer and amyotrophic lateral sclerosis (ALS)." (PMID 26988030, 2016).
hepatocellular carcinoma (19 papers, 2011 to 2025). A malignant tumor that arises from hepatocytes. "The level of GPNMB is low in normal hepatocytes but higher in hepatocellular carcinoma cells according to research." (PMID 35784282, 2022). "Dysfunction of GPNMB has been recognized in metastatic prostate cancer, hepatocellular carcinoma, and other cancers." (PMID 30484490, 2018). "The dysregulation of GPNMB expression has been reported in many types of cancer, including hepatocellular carcinoma, malignant gliomas, and metastatic prostate cancer, and it is associated with the invasion and metastasis of tumor cells." (PMID 30484490, 2018). "GPNMB is implicated in immunosuppression and cancer progression, and UAP1L1 plays a critical role in the proliferation of hepatocellular carcinoma cells, whose knockdown significantly decreases human hepatoma cell proliferation." (PMID 37595802, 2023). "In hepatocellular carcinoma, ECs promote CD8+ T-cell exhaustion through the upregulation of glycoprotein nonmetastatic melanoma protein B (GPNMB)." (PMID 40650130, 2025). "These cells express the marker genes CD9 and TREM2, a tumor suppressor in hepatocellular carcinoma, as well as the markers CAPG and GPNMB." (PMID 33332768, 2020). "Moreover, studies have shown that FTO expression is upregulated in hepatocellular carcinoma tumors, and targeting the FTO/m6A/GPNMB axis significantly inhibits tumor growth and metastasis while enhancing immune activation." (PMID 39980685, 2025). "In hepatocellular carcinoma, tumor endothelial cells induce tumor-infiltrating T cell exhaustion by expressing glycoprotein nonmetastatic melanoma protein B (GPNMB)." (PMID 39325128, 2024). "In human hepatic carcinoma tissue and in the malignant hepatic cell line HepG2, ARSB activity was reduced compared to normal control, and the expression of Glycoprotein Nonmetastatic Melanoma Protein B (GPNMB) was increased in hepatic tissue of ARSB null mice and ARSB silenced hepatic cells." (PMID 36361933, 2022). "Interestingly, TAM-like macrophages in hepatocellular carcinoma highly express two genes: FPN1 and GPNMB." (PMID 33714956, 2021). "For example, RGCC, SPP1 (osteopontin), GPNMB, and APOE are highly expressed in hepatocellular carcinoma (HCC), whereas PLVAP (PV1), CD276 (B7-H3), and ESM1 are predominantly expressed in glioblastoma (GBM)." (PMID 41303611, 2025). "Moreover, C1Q+ macrophages in sAH express GPNMB, TREM2, SPP1, and CD9, resembling LAMs, which are reported in liver cirrhosis and hepatocellular carcinoma (HCC)." (PMID 40962953, 2025). "have demonstrated that hepatocellular carcinoma-associated ECs can induce tumor-infiltrating T cell exhaustion through the expression of the glycoprotein nonmetastatic melanoma protein B (GPNMB), suggesting that GPNMB might be a novel therapeutic target in hepatocellular carcinoma." (PMID 38426109, 2024). "In addition, glycoprotein nonmetastatic melanoma protein B (GPNMB), a downstream target of FTO that reduces its m6A abundance, is packaged into small extracellular vesicles (sEVs) derived from hepatocellular carcinoma cells." (PMID 40986143, 2025).
glioblastoma (18 papers, 2010 to 2025). The most malignant astrocytic tumor (WHO grade IV). "GPNMB-expressing TAMs are specifically indicative of glioblastoma and are associated with poor prognosis in glioblastoma patients." (PMID 39516356, 2024). "Glioblastoma multiforme patients with increased mRNA and protein levels of GPNMB were reported to have a significantly higher risk of death." (PMID 29299134, 2017). "High GPNMB expression was found to be associated with poor prognosis in human glioblastoma." (PMID 31097021, 2019). "Emerging Technologies: CRISPR-Cas9 editing of GPNMB in glioblastoma cells reduced invasion by 70%, while nanoparticle-mediated delivery of GPNMB siRNA improved targeting and reduced off-tumor effects in lung cancer models." (PMID 41180454, 2025). "Increased mRNA and protein levels of GPNMB in the biopsy samples of patients with glioblastoma multiforme correlated with a higher survival rate." (PMID 32610669, 2020). "In a study on glioblastoma multiforme patients, it was found that 35 out of 50 were positive (70%) for GPNMB/OA mRNA and 52 of 79 (66%) showed detectable GPNMB/OA in a membraneous and cytoplasmic pattern." (PMID 26883195, 2016). "In glioblastoma, GPNMB-high macrophages can induce mesenchymal transformation." (PMID 38906852, 2024). "Furthermore, GPNMB has also been indicated as a potential molecular therapeutic target in patients with glioblastoma." (PMID 31097021, 2019). "Thus, the overexpression of GPNMB is a promising target for immunotherapy for glioblastoma multiforme." (PMID 28347118, 2015). "Interestingly, GPNMB expression in melanoblasts and osteoclasts was shown to be dependent on MITF, and in human glioblastoma cells this transcription factor is activated by PI3K/Akt and GSK3β signaling." (PMID 25889792, 2015).
Gaucher disease (17 papers, 2015 to 2025). Gaucher disease (GD) is a lysosomal storage disorder encompassing three main forms (types 1, 2 and 3), a fetal form and a variant with cardiac involvement (Gaucher disease - ophthalmoplegia - cardiovascular calcification or Gaucher-like disease). "The association between elevated gpNMB concentrations and these clinical features in Gaucher disease warrants further investigation." (PMID 41152894, 2025). "Given the established role of glucosylsphingosine (GlcSph) as a key pathogenic molecule in Gaucher disease, its association with plasma gpNMB concentrations was investigated." (PMID 41152894, 2025). "Our findings indicate that the association of plasma gpNMB with liver cirrhosis, gammopathy and pulmonary disease in Gaucher disease warrants further investigation." (PMID 41152894, 2025). "Earlier work also described accumulation of GPNMB positive foamy cells in the liver of Npc1−/− mice, resembling Gaucher cells during a primary GCase deficiency (Gaucher disease)." (PMID 33802460, 2021). "Quantitative proteomic analyses identified GPNMB as a marker of brain pathology in Gaucher disease, a recessive inherited metabolic disorder caused by defects in the glucosylceramidase gene." (PMID 33947460, 2021). "GPNMB elevations have also been shown in the brains, CSF, and plasma of the lysosomal storage disorders’ Gaucher disease and Niemann-Pick type C, further supporting an association of GPNMB in glycolipid dysregulation." (PMID 31331333, 2019). "Intriguingly, GPNMB mRNA and protein expression have also been linked to Gaucher’s disease and Niemann Pick type C, two lysosomal storage disorders." (PMID 28391543, 2017). "Plasma concentrations of gpNMB were significantly higher in patients with Gaucher disease (mean: 200.9; range: 9.8-1643 ng/ml) compared with healthy controls (mean: 35.1; range.: 10.1- 125 ng/ml), including those receiving enzyme replacement therapy (ERT)." (PMID 41152894, 2025). "Nonetheless, plasma gpNMB concentrations were markedly increased, indicating residual activity of their Gaucher disease." (PMID 41152894, 2025). "gpnmb expression is elevated in the livers of Gaucher disease zebrafish, and gpNMB has been identified as a marker for glucosylceramide-laden macrophages in both Gaucher disease patients and mice." (PMID 37183607, 2023). "Previous studies have suggested significant increases of GPNMB in other lysosomal diseases, such as Gaucher disease and lipid metabolic disorders, in animal models as well as in NPC." (PMID 33466390, 2021). "Elevated levels of GPNMB have also been shown in brains, CSF and plasma of Gaucher disease patients." (PMID 30340518, 2018). "In conclusion, gpNMB acts as a marker for glucosylceramide‐laden macrophages in man and mouse and gpNMB should be considered as candidate biomarker for Gaucher disease in treatment monitoring." (PMID 27642553, 2016). "Our data suggest that GPNMB can be used as a marker to quantify neuropathology in Gaucher disease patients and as a marker of treatment efficacy once suitable treatments towards the neurological symptoms of Gaucher disease become available." (PMID 25775479, 2015). "Neuropathology in Gaucher disease may be quantified using gpNMB, which has been proposed as a new useful biomarker due to its expression in activated microglia." (PMID 41152894, 2025). "In conclusion, our finding of markedly elevated plasma gpNMB levels in symptomatic Gaucher patients warrants further investigations regarding its applicability in the clinical management of Gaucher disease as well as its role in the peculiar pathophysiology of the disorder." (PMID 27642553, 2016). "Moreover, GPNMB levels in the CSF correlate with disease severity in a mouse model of Gaucher disease." (PMID 25775479, 2015). "GPNMB was also elevated in brain samples from patients with type 2 and 3 Gaucher disease." (PMID 25775479, 2015).
Gaucher disease (continued). "Using three independent techniques, including quantitative global proteomic analysis of cerebrospinal fluid (CSF) in samples from Gaucher disease patients that display neurological symptoms, we demonstrate a correlation between the severity of symptoms and GPNMB levels." (PMID 25775479, 2015). "Therefore, high circulating or local gpNMB release might be responsible for pathological changes in extracellular matrix and the development of tissue fibrosis, which is a feature of Gaucher disease infiltration in the lung, liver, and spleen." (PMID 41152894, 2025). "More recently, CHIT1 has been described as a prognostic biomarker for early MS, and soluble GPNMB, which is secreted from different cell types through a disintegrin and metalloproteinase 10 sheddase activity, was identified as a further biomarker of Gaucher disease." (PMID 29312322, 2017). "In Gaucher disease, GlcCer-laden macrophages excessively produce the chitinase chitotriosidase, the chemokine CCL18 (C−C motif chemokine ligand 18) and GPNMB (glycoprotein nmb)." (PMID 33802460, 2021). "Previous reports found that GPNMB was elevated in the serum of type I Gaucher disease, but not significantly different in AD patients, compared to healthy controls." (PMID 33028409, 2020). "We now identify a protein, glycoprotein non-metastatic B (GPNMB), that acts as an authentic marker of brain pathology in neurological forms of Gaucher disease." (PMID 25775479, 2015). "However, plasma gpNMB neither differentiated between the neuronopathic subtypes of Gaucher disease nor idiopathic Parkinson’s disease." (PMID 41152894, 2025).
Obesity (17 papers, 2015 to 2025). Accumulation of substantial excess body fat. "In this previous study, DBA2J mice, in which missense mutation of GPNMB (R150X) occurs naturally, was also investigated for obesity-related metabolic disorders." (PMID 34582891, 2021). "Of note, male GPNMB-KO mice showed exacerbated metabolic disorders associated with obesity, despite similar adiposity." (PMID 34582891, 2021). "Here, we investigated the role of GPNMB in obesity-related metabolic disorders utilizing GPNMB-deficient mice." (PMID 34582891, 2021). "Here, we explored a role of GPNMB in obesity using GPNMB-deficient mice and revealed its protective role in obesity-related metabolic disorders by reducing macrophage inflammatory capacities." (PMID 34582891, 2021). "In a recent study, GPNMB was reported to be a risk factor for obesity and diabetes." (PMID 38790981, 2024). "Our data reveal that GPNMB negatively regulates macrophage inflammatory capacities and ameliorates the WAT inflammation in obesity; therefore we conclude that GPNMB is a promising therapeutic target for the treatment of metabolic disorders associated with obesity." (PMID 34582891, 2021). "Therefore, a role of GPNMB in obesity and its-associated metabolic disorders remains controversial." (PMID 34582891, 2021). "Expressed in macrophages and hypertrophied adipocytes, gpNMB was also reported to play a crucial role during obesity in white adipose tissue inflammation, which is critical in obesity-related metabolic disorders in mouse models." (PMID 41152894, 2025). "In an earlier study by our group, an increase in the circulating level of GPNMB was observed in people with obesity and T2D." (PMID 38790981, 2024). "A distinct correlation has been established between GPNMB and obesity, wherein GPNMB plays a protective role, with anti-inflammatory effects preventing the progression of obesity-related metabolic complications." (PMID 38790981, 2024). "Study has identified the role of liver-secreted GPNMB in exacerbating obesity and insulin resistance by promoting lipogenesis." (PMID 36875463, 2023). "GPNMB was also reported to protect against obesity-related inflammation by inhibition of inflammatory cytokine secretion from macrophages." (PMID 36430499, 2022). "In nonalcoholic steatosis, transgenic mice containing an aP2 promoter-driven GPNMB overexpression showed decreased fat accumulation and fibrosis in the liver in an obesity model when compared to obese D2 mice." (PMID 34054862, 2021). "We clearly showed that macrophages are critically involved in the exacerbated obesity-related metabolic disorders in GPNMB-KO mice by macrophages depletion experiments." (PMID 34582891, 2021). "On the other hand, another previous report showed that GPNMB inhibition by a neutralizing antibody or liver-specific knockdown reduced body weight and improved obesity-related metabolic disorders." (PMID 34582891, 2021). "To elucidate a critical role of macrophages in the deteriorated WAT inflammation and the exacerbated obesity-related metabolic disorders in GPNMB-KO mice, we depleted macrophages in mice using clodronate liposomes." (PMID 34582891, 2021). "To elucidate a role of GPNMB in obesity, we generated mice with target deletion of GPNMB (GPNMB-KO) and analyzed their metabolic phenotype." (PMID 34582891, 2021). "One of genes identified encodes GPNMB, and we found that its expression in the WAT was substantially enhanced during obesity." (PMID 34582891, 2021). "Nonetheless, insulin and glucose tolerance tests revealed significant obesity-related metabolic disorders in GPNMB-KO mice compared with WT mice fed with HFD." (PMID 34582891, 2021). "GPNMB is a transmembrane protein involved in adipose tissue-derived inflammation in a mouse model of obesity." (PMID 32825633, 2020).